DEFB1 (defensin beta 1)
Diseases named in the same sentence as DEFB1 in open-access papers (continued):
Sharing a sentence is not in itself a finding about the gene and the disease.
infection (54 papers, 2005 to 2025). The state of being infected such as from the introduction of a foreign agent such as serum, vaccine, antigenic substance or organism. "Among them, only the gene encoding hBD1, DEFB1, elevated most significantly after infection at both 48 h and 72 h post infection." (PMID 38397085, 2024). "Foxa2 is involved in the transcriptional regulation of DEFB1, and downregulation of DEFB1 due to suppression of Foxa2 expression is likely to contribute to increased infection risk in the Th2-dominated airway inflammation." (PMID 31881038, 2019). "Previous studies suggested an association of an impaired activity or secretion of DEFB1 with decreased clearance of bacteria and increased risk of infections." (PMID 31881038, 2019). "Studies on DEFB1-deficient mice showed compromised innate immunity and increased infection risk; however, adaptive immunity was functional when DEFB1 was mutated." (PMID 31881038, 2019). "The impaired secretion of DEFB1 may be responsible for the increased risk of infection in the Th2-dominated airway inflammation." (PMID 31881038, 2019). "Moreover, DEFB1-deficient mice are more susceptible to infection with Candida albicans and exhibit elevated systemic fungal burdens compared with wild-type mice." (PMID 28181499, 2017). "Cryptosporidium also delivers RNA transcripts like Cdg7_FLc_1000, which downregulate beta-defensin 1 (DEFB1), compromising the epithelial barrier and promoting infection." (PMID 40137692, 2025). "Upon H37Rv infection, Defb1−/− mice exhibited a significant increase in lung bacterial load (p < 0.0001)." (PMID 38397085, 2024). "On the contrary, infection was associated with a trend towards an increase in DEFB1 and DEFB103 transcript levels in adults, as well as DEFB1 and DEFB4A transcript levels in elderly subjects." (PMID 34858406, 2021). "The combined hormones induced the expression of BNBD10, LAP and DEFB1, which were maintained after infection." (PMID 32605209, 2020). "Although DEFBs are found increasingly in different cells or organs, DEFB1 is expressed constitutively in the airway epithelial cells, whereas the induced expression of other defensins is seen during infections." (PMID 31881038, 2019). "DefB1, the gene responsible for beta-defensin-1 produced largely by epithelial cells, is upregulated early and for an extended period in the time course between days 2 and 4 post-infection." (PMID 26230099, 2015). "In wild type mice, bladder Defb1 mRNA levels decreased as early as two hours post-infection and reached a nadir by six hours." (PMID 24204930, 2013). "Together, these findings suggest a mechanism which supports genetic studies that have demonstrated a correlation between the DEFB1 5' UTR -44 SNP G allele and protection from various types of infection." (PMID 19712472, 2009). "DEFB1 is known as a multifunctional mediator in infection and inflammation." (PMID 35462887, 2022). "Hence, future studies need to choose wild-type Mtb to establish animal infection models and alveolar macrophages for in vitro experiments to explore the regulation function of Nos2 expression on NO, ROS, and Defb1, which will resolve these limitations of the study." (PMID 39412514, 2024). "During infection, other types of DEFBs are induced by inflammatory factors, thus suggesting that DEFB1 may play a pivotal role in defense against invading pathogens when the host is confronted by a small number of microbes or in the early stages of an infection." (PMID 31881038, 2019). "However, in A549 cells, we found that binding of CEBPB to motif 1 and motif 2 in site 1 may have an inhibitory effect on DEFB1 transcription, as truncation of motif 1, motif 2, or motif 1+2 (site 1 as a whole) increased DEFB1 transcription after H37Rv infection." (PMID 38397085, 2024). "Thus, DEFB1 depletion might enhance the probability of developing infections from an early stage." (PMID 31881038, 2019).
infection (continued). "Anti-microbial peptides DefB1 and S100A8 are upregulated in colons of C. difficile-infected mice at distinct time points during infection." (PMID 26230099, 2015). "Consequently, we analyzed the mRNA levels of the proinflammatory cytokines TNF-α, IL-1β, and IL-6 and the anti-inflammatory cytokine IL-10, as well as the antimicrobial peptides TAP, DEFB1, and BNBD5 in LEAS-pretreated bMECs before and after infection." (PMID 31612151, 2019). "Because DEFB1 is believed to act as a baseline defense molecule in the absence of infection and inflammation, we focused on the role of epigenetic changes in regulation of DEFB1 gene expression." (PMID 21818276, 2011). "To investigate whether the transcriptional activity of CEBPB on DEFB1 is regulated by the AMPK and mTOR pathways and the resulting truncation of CEBPB, we first examined the activation of AMPK and mTOR in AEC-II cells after H37Rv infection." (PMID 38397085, 2024). "With the progression of the infection a more equilibrated immunological balance is observed, with 6 genes showing significant transcription up-regulation: IFN-γ, IL-5, TNF-α, TGF-βR1, IL-21 and IL-23 and 4 extra genes showing significant down-regulation: DEFB1, CD163, IL-13 and IL-18." (PMID 26589145, 2015). "In addition, the polymorphisms were not important predictors of susceptibility to infection, suggesting that they do not influence DEFA1/DEFA3-mediated or DEFB1-mediated responses to infection." (PMID 16700921, 2006). "Consistent with upregulation of CEBPB and hBD1 following H37Rv-infection, the binding of CEBPB to the DEFB1 promoter increased in H37Rv-infected AEC-II cells compared with in cells without infection." (PMID 38397085, 2024). "Our findings showed that supplementing the rabbits with TQN significantly (p < 0.05) upregulated the transcription levels of IL-10, TLR-4, DEFB1 and TLR-2 genes comparing with the control non-supplemented rabbits at 96 h post-infection with P. multocida strain." (PMID 38292130, 2023).
cancer (41 papers, 2008 to 2026). A tumor composed of atypical neoplastic, often pleomorphic cells that invade other tissues. "Among these IRGs, a two-gene signature consisting of CCL8 and DEFB1 was found to be closely associated with patient prognosis using the cancer genome atlas (TCGA) database." (PMID 32719391, 2020). "Eight genes are in the overlap of all subgroups, among them immune-related genes (DEFB1, AOC1, JCHAIN) as well as genes (215780_s_at/SET, SPP1) that were reported in the literature to be associated with different types of cancer." (PMID 34876106, 2021). "DEFB1 and TYK2 protein expression did not match the intergroup differences between cancer and adjacent normal tissues in the transcriptome." (PMID 38375157, 2024). "The expression of PIGR, DEFB1, LTF, CLU, SCGB2A1 and S100A7, while having a positive role in cancer elimination, were either downregulated or not changed in all or some of the BC subtypes." (PMID 38589404, 2024).
bacterial infection (7 papers, 2011 to 2024). "DEFB1 is an antimicrobial peptide associated with innate immunity, and bacterial infection-induced inflammation has been associated with depression." (PMID 29317604, 2018). "DEFB1 is an antimicrobial peptide that plays a role in host defense against bacterial infection." (PMID 29317604, 2018).
digestive diseases (1 paper, 2017). "Multiple studies reported that the low expression of DEFB1, due to genetic polymorphisms, is associated with the pathogenesis of digestive diseases." (PMID 28272373, 2017). "In contrast, other studies showed no such correlation between DEFB1 genetic polymorphisms and digestive diseases." (PMID 28272373, 2017).
DEFB1 also shares sentences with these, for which no sentence is quoted: COVID-19 (6 papers); colitis (5); viral infection (5); colorectal cancer (4); diabetes (4); adenocarcinoma (3); autoimmune disease (3); chronic periodontitis (3); HIV-1 infection (3); renal clear cell carcinomas (3); rotator cuff tears (3); salivary gland tumour (3); adenoma (2); basal cell carcinoma (2); bladder cancer (2); corneal infection (2); epidermoid carcinoma (2); infectious disease (2); leukoplakia (2); type 2 diabetes (2); vaginitis (2); acute lymphoblastic leukaemia (1); acute pancreatitis (1); adenoid cystic carcinoma (1); aggressive periodontitis (1); asthenozoospermia (1); autoimmune disorders (1); bacteremia (1); bacterial pneumonia (1); benign salivary gland tumours (1).
A further 58 diseases each share a sentence with DEFB1 in 1 paper.